TPP1 (tripeptidyl peptidase 1)
Diseases named in the same sentence as TPP1 in open-access papers (continued):
Sharing a sentence is not in itself a finding about the gene and the disease.
cervical cancer (3 papers, 2017 to 2025). A primary or metastatic malignant neoplasm involving the cervix. "High expression of TPP1 (HR = 2.61, 95% CI 1.23–5.51) and co-high expression of TPP1 and hTERT (HR = 2.38, 95% CI 1.28–4.43) were independently associated with worse survival in cervical cancer patients." (PMID 38722833, 2024). "Association of TPP1 expression and clinicopathological characteristics of cervical cancer." (PMID 38722833, 2024). "This study may provide important clues of using TPP1 as both a risk biomarker and a prognostic factor in cervical cancer." (PMID 38722833, 2024). "We analyzed the association of TPP1 expression with cervical cancer pathogenesis and prognosis." (PMID 38722833, 2024). "In research on cervical cancer, it has also been found that high expression of TPP1 is associated with cervical intraepithelial neoplasia (CIN) and a high risk of cervical cancer." (PMID 39871386, 2025). "In conclusion, TPP1 expression increased significantly in late precursor lesions (CIN 3) and cervical cancers compared and high expression of TPP1 indicated worse survival in cervical cancer." (PMID 38722833, 2024). "For the clinical-pathological factors of cervical cancer, TPP1 expression was related to pathological differentiation (P = 0.006), lymphatic invasion (P = 0.047), and vaginal invasion (P = 0.022)." (PMID 38722833, 2024). "Compared with cervical cancer patients with low TPP1 expression, significantly worse survival was found in those with high expression of TPP1 (Plog-rank = 0.047)." (PMID 38722833, 2024). "In agreement with increased proportion of high TPP1 expression detected in CINs and cervical cancer samples, higher expression of the TPP1 gene was validated in external and publicly available databases (GSE7803 and Oncomine)." (PMID 38722833, 2024). "It was interesting to note that high TPP1 expression was an independent predictor of poor survival for cervical cancer and related to tumor differentiation, lymphatic invasion, and vagina invasion, indicators of aggressiveness of this disease." (PMID 38722833, 2024). "The mechanism of how TPP1 interacts with hTERT and how TPP1 promotes the malignant phenotype of cervical cancer requires further investigation." (PMID 38722833, 2024). "The present study indicated that TPP1 was related to the progression of cervical cancer malignancy, as shown by the constant increase of high TPP1 expression rates from the normal cervix, CIN 1, CIN 2, CIN 3 to SCC and AC/ASC." (PMID 38722833, 2024). "To explore the regulatory effect of TPP1 on hTERT, we transfected the TPP1-siRNA into three human cervical cancer cell lines." (PMID 38722833, 2024). "TPP1 expression positively correlated with the expression of hTERT in cervical cancer, and depletion of TPP1 substantially decreased hTERT expression." (PMID 38722833, 2024). "We further analyzed the impact of TPP1 expression on the overall survival of cervical cancer patients by calculating the hazard ratio (HR) with 95% confidence intervals (CIs) using the multivariable-adjusted Cox regression model." (PMID 38722833, 2024). "It is unclear how telomere-binding protein TPP1 interacts with human telomerase reverse transcriptase (hTERT) and influences cervical cancer development and progression." (PMID 38722833, 2024). "When compared with normal tissues, TPP1 was higher expressed in CINs (P<0.05) and strongly expressed in cervical carcinoma (P<0.001)." (PMID 38722833, 2024). "In addition, high TPP1 expression and co-highly expressed with hTERT were both independent predictors of poor survival for cervical cancer patients." (PMID 38722833, 2024). "This study indicate high expression of TPP1 may be an early event during cervical cancer development and a prognostic factor for survival in cervical cancer." (PMID 38722833, 2024). "TPP1 and hTERT expression was correlated and high expression of TPP1 was associated with high risk of CIN 3 and cervical cancer and could predict a worse survival in cervical cancer." (PMID 38722833, 2024).
cervical cancer (continued). "TPP1 was knocked down by siRNA in three cervical cancer cell lines." (PMID 38722833, 2024). "Interestingly, we found that mRNA expression of TPP1 was positively correlated with the expression of MKI67, suggesting that TPP1 could be linked to the proliferation and malignancy of cervical cancer." (PMID 38722833, 2024). "The mechanisms of TPP1 in determining cervical cancer development remain unclear." (PMID 38722833, 2024). "It is possible that TPP1 expression is elevated earlier than the activation of hTERT and that hTERT activation by TPP1 signaling pathway might lead to the occurrence or progression of cervical cancer." (PMID 38722833, 2024). "As an exploration, we also assessed the correlation between TPP1 and MKI67 gene expression using TCGA data from the GEPIA database in cervical cancer." (PMID 38722833, 2024). "Similar to TPP1, the percentage of patients with high expression of hTERT increased in CIN3 and cervical cancers." (PMID 38722833, 2024). "In this retrospective study, TPP1 expression was assessed in a continuum of cervical lesions, from normal cervix, cervical intraepithelial neoplasia (CIN) 1 to 3, to cervical cancer in an institutional patient cohort." (PMID 38722833, 2024). "Compared with the normal cervix, a significantly increased proportion of high TPP1 expression was found for CIN 3 (P = 0.002) and cervical cancers (P<0.001)." (PMID 38722833, 2024). "Our study suggested that TPP1 might be a potential predictive biomarker for CIN 3 and cervical cancers." (PMID 38722833, 2024). "But whether TPP1 could serve as an independent biomarker in pathogenesis and prognosis in cervical cancer has not been fully investigated." (PMID 38722833, 2024).
aplastic anaemia (2 papers, 2022 to 2024). "TPP1 mutations (D224A) are linked to family melanoma, aplastic anaemia, and glioblastoma." (PMID 39578854, 2024).
autism (2 papers, 2025). Persistent deficits in social interaction and communication and interaction as well as a markedly restricted repertoire of activity and interest as well as repetitive patterns of behavior. "In VPA females’ model of autism, nooclerin exerted the most pronounced influence on alterations in the transcriptional activities of the tnks genes, telomerase (Tep1, Dkc1) and the shelterin complex (Terf2ip, Pot1a, Tinf2, Tpp1, Trf1 - 2) in the hippocampus." (PMID 40272729, 2025).
chronic lymphocytic leukaemia (2 papers, 2017 to 2025). "In this context, mutations in the following genes of the shelterin protein complex (POT1, TPP1, TERF2IP, and TINF2) have also been associated with familial melanoma, glioma, and chronic lymphocytic leukemia (CLL)." (PMID 40563586, 2025).
esophageal cancer (2 papers, 2024 to 2025). A primary or metastatic malignant neoplasm involving the esophagus. "The results revealed that TPP1 was also overexpressed in several other cancers, such as esophageal carcinoma, stomach adenocarcinoma, and liver hepatocellular carcinoma, and increased expression of TPP1 was associated with worse survival in these cancers." (PMID 38722833, 2024). "For example, in esophageal cancer, the expression of TPP1 is sharply upregulated and its knockdown can markedly reduce the migration ability of tumor cells by causing cell cycle arrest at the G1 phase." (PMID 41338460, 2025). "Recent studies have shown that TPP1 is abnormally overexpressed in a variety of tumors (such as esophageal cancer, cervical cancer, and melanoma), promoting telomere elongation through the recruitment of telomerase and maintaining the replicative immortality of cancer cells." (PMID 41338460, 2025).
familial melanoma (2 papers, 2017 to 2022). Familial melanoma (FM) is a rare inherited form of melanoma characterized by development of histologically confirmed melanoma in two first degrees relatives or more relatives in an affected family. "For the shelterin component TPP1 (encoded by ACD), nonsense mutations are hypothesized to remove a negative regulation on telomerase elongation, and these mutations have been implicated in familial melanoma." (PMID 35609925, 2022).
infertile (2 papers, 2020 to 2022). "Together, our data demonstrate that the TPP1 K82∆ mutation reduces mouse germline stem cell count and culminates in diminished gamete production that causes infertility in males." (PMID 34645668, 2022). "Taken together, our data strongly suggests a role for TPP1 in endometrial receptivity via its effects on epithelial cell adhesion and suggests reduced levels associated with unexplained infertility may contribute to implantation failure." (PMID 33317560, 2020). "Compared to fertile tissues, mid-secretory tissues from women with infertility exhibited reduced staining intensity of TPP1 specifically in luminal epithelial cells." (PMID 33317560, 2020). "In the current study, TPP1 was widely expressed in the fertile endometrium across the menstrual cycle but was reduced in mid-secretory infertile tissues only in the luminal epithelium, conferring a likely location- and cell-specific function for TPP1." (PMID 33317560, 2020). "Staining of mid-secretory endometrial tissues of women with normal fertility and primary unexplained infertility showed reduced immunostaining intensity of TPP1 in luminal epithelial cells of infertile tissues compared to fertile tissues." (PMID 33317560, 2020). "More importantly, compared to mid-secretory fertile endometrial tissues, infertile tissues exhibited significantly reduced TPP1 immunostaining intensity in the luminal epithelium." (PMID 33317560, 2020). "In stark contrast, K82∆ mice showed reproductive defects that ultimately resulted in sterility in late generations, suggesting that telomere shortening induced by a single amino acid deletion in TPP1 is sufficient to elicit a mouse germline defect and infertility." (PMID 34645668, 2022). "Intriguingly, both TPP1 K82∆ mice and previously characterized telomerase knockout mice show no spontaneous bone marrow failure but rather succumb to infertility at steady-state." (PMID 34645668, 2022). "TPP1 staining intensity scores in the endometrial glandular epithelium did not change between fertile and infertile tissues during receptivity cells." (PMID 33317560, 2020).
leukemia (2 papers, 2020 to 2025). A malignant (clonal) hematologic disorder, involving hematopoietic stem cells and characterized by the presence of primitive or atypical myeloid or lymphoid cells in the bone marrow and the blood. "Further studies are needed to translate the underlying molecular mechanisms implicating TPP1 in apoptosis inhibition of leukemia cells." (PMID 32033110, 2020). "In addition, TPP1 mutations are less commonly observed in leukemias; however, they have been detected in AML and myelodysplastic syndromes (MDS), which may impact telomere stability." (PMID 40563586, 2025). "There is growing evidence linking the pathophysiology and development of leukemias to mutations in the expression of numerous shelterin components, especially POT1, TPP1, and TIN2." (PMID 40563586, 2025). "Altogether, these data strongly support a role for TPP1 p.G223V mutant in promoting leukemia cell maintenance." (PMID 32033110, 2020).
malaria (2 papers, 2013 to 2022). Malaria is a serious and sometimes fatal disease caused by a parasite that commonly infects a certain type of mosquito which feeds on humans. "TPP-1 applies to medications for acute malaria treatment, with essential parameters that include activity against resistant parasites, rapid onset of action, and a large (>12 log10) reduction in asexual parasite load." (PMID 36061376, 2022).
stomach adenocarcinoma (2 papers, 2024 to 2025). "According to Starbase analysis, TPP1 expressions were materially higher in stomach adenocarcinoma tissues comparing to normal tissues." (PMID 41338460, 2025).
adenosquamous carcinoma (1 paper, 2024). A carcinoma composed of malignant glandular cells and malignant squamous cells. "Expressions of TPP1 and hTERT were highly correlated in CIN 3 (Kappa statistics = 0.50, P = 0.005), squamous cell carcinoma (Kappa statistics = 0.22, P = 0.011), and adenocarcinoma/adenosquamous carcinoma (Kappa statistics = 0.77, P = 0.001)." (PMID 38722833, 2024).
allergies (1 paper, 2025). "However, an ERT approach for CLN2 would require biweekly life-long administrations of TPP1 both to the retina and the brain, resulting in a significant reduction of the quality of life of patients and an increased risk of adverse reactions (infections and allergies)." (PMID 40706588, 2025).
asthma (1 paper, 2015). "It was hypothesized that the identified downregulation of M6PR, TPP1, GLB1, NEU1, ACP2, LAMP1 and HGSNAT leads to disorders of lysosome function, which results in asthma by causing T-cell dysfunction." (PMID 25633562, 2015).
atopic asthma (1 paper, 2015). An asthma that is characterized by symptoms that are triggered by an allergic reaction caused by inhaled allergens such as dust mite allergen, pet dander, pollen and mold. "Among the genes identified in the present study (M6PR, TPP1, GLB1, NEU1, ACP2, LAMP1 and HGSNAT) that were significantly associated with lysosomal function, only TPP1 has been confirmed as being associated with atopic asthma." (PMID 25633562, 2015). "TPP1 has previously been established as a shared or restricted regulatory dendritic cell (DC) marker, which has been suggested to have an important role in the development of atopic asthma." (PMID 25633562, 2015).
bladder cancer (1 paper, 2020). "Taken together, TPP1, TMPRSS2 and FOLR1 could all be possible prognostic markers and treatment targets in bladder cancer." (PMID 32249794, 2020).
chronic lung disease (1 paper, 2024). According to the definitions of the American and British Thoracic Societies, including pulmonary functional tests, X-rays, and CT scans for items such as fibrosis, bronchiectasis, bullae, emphysema, nodular or lymphomatous abnormalities. "Overall, TPP1 plays an important role in maintaining lung homeostasis and injurious responses with age‐dependent effects in response to CS in chronic lung diseases and COPD/emphysema." (PMID 38344410, 2024).
fibrosis (1 paper, 2022). the formation of excess fibrous connective tissue in an organ or tissue in a reparative or reactive process. "Alternatively, telomere uncapping caused by stress-induced telomeric shelterin protein TPP1 degradation mediates DNA damage response, pulmonary senescence and fibrosis." (PMID 35269498, 2022).
gastric tumor (1 paper, 2020). "Using gastric tumor and adjacent normal tissue specimens collected in our hospital, we showed that MYO5A, PLTP, and TPP1 exhibited higher mRNA and protein expression in tumors than in normal tissue." (PMID 32735728, 2020).
head and neck cancer (1 paper, 2024). A primary or metastatic malignant neoplasm affecting the head and neck. "We identified one protein for each of bladder [WAS, 0.54 (0.39–0.73)], brain [GFAP, 1.55 (1.31–1.86)], and head and neck cancers [TPP1, 1.33 (1.16–1.52)]." (PMID 38750076, 2024).
Hoyeraal-Hreidarsson syndrome (1 paper, 2023). Hoyeraal-Hreidarsson syndrome (HHS) is a very rare X-linked recessive disorder considered to be a severe variant of dyskeratosis congenita characterized by intrauterine growth retardation, microcephaly, cerebellar hypoplasia, progressive combined immune deficiency and aplastic anemia. "The TPP1-telomerase structures herein presented represent attractive pharmacological targets for drug design of innovative therapeutics in cancer and telomeropathies like Hoyeraal-Hreidarsson syndrome." (PMID 37935941, 2023).
Hyperglycemia (1 paper, 2022). An increased concentration of glucose in the blood. "TPP-1 could increase significantly the contents of insulin and total superoxide dismutase of the hyperglycemia mice, whereas TPP-1 could decrease the levels of biochemical indexes, including MDA, creatinine, triglyceride, LDL-C, and blood urea nitrogen." (PMID 36159471, 2022). "Moreover, TPP-1 could reduce the blood glucose levels in hyperglycemia mice." (PMID 36159471, 2022).
ileum cancer (1 paper, 2017). "Other protein-encoding genes (FGL2, CTSB, TPP1, SLCO2B1, NARF and JTB) have disease related functions, such as viral hepatitis and ileum cancer." (PMID 28401895, 2017).
invasive carcinoma (1 paper, 2020). A carcinoma that is not confined to the epithelium, and has spread to the surrounding stroma. "Tripeptidyl-peptidase 1 is a lysosomal serine protease whose enzymatic activity has been observed in pancreatic mucinous cysts with a high probability to develop into invasive carcinoma." (PMID 32942548, 2020).
larynx squamous cell carcinoma (1 paper, 2023). "Moreover, in larynx squamous cell carcinoma, the expression of TPP1 is elevated, and TPP1 may be a prognostic marker for response to radiotherapy for patients." (PMID 37087456, 2023).
lung adenocarcinoma (1 paper, 2024). A carcinoma that arises from the lung and is characterized by the presence of malignant glandular epithelial cells. "Significantly increased expression of PCNA and Ki67 in TPP1 CreCC10 corroborates with a high index of these proteins in human lung adenocarcinoma." (PMID 38344410, 2024).
lung carcinoma (1 paper, 2020). "The hemoglobin subunit beta was highly expressed in serum of ovarian cancer patients, while tripeptidyl-peptidase 1 was proposed as a biomarker for colorectal and lung cancer." (PMID 32942548, 2020).
lung disease (1 paper, 2024). "However, it is unknown if the conditional removal of TPP1 from Club cells can induce lung disease pathogenesis caused by tobacco smoke exposure." (PMID 38344410, 2024).
lupus (1 paper, 2024). "Other promising urine biomarkers—such as Angptl4, L-selectin, TPP1, and TGFβ1—also had high ROC AUC values for distinguishing patients with lupus and AR from those with iSLE, with the combination of Angptl4, L-selectin, and TPP1 yielding the highest discrimination with an AUC of 0.97." (PMID 38673612, 2024).
mucopolysaccharidosis (1 paper, 2020). A group of autosomal recessive or X-linked inherited lysosomal storage disorders affecting the metabolism of mucopolysaccharides, resulting in the accumulation of mucopolysaccharides in the body. "In the second, a further 6 LSD of the mucopolysaccharidosis for MPS II, IIIB, IVA, VI, VII and TPP1 (CLN2)." (PMID 33073010, 2020).
myocardial infarction (1 paper, 2020). Gross necrosis of the myocardium, as a result of interruption of the blood supply to the area, as in coronary thrombosis. "We treated MSCs with H2O2 to induce oxidative stress to mimic the microenvironment of myocardial infarction, and we confirmed the importance of TPP1 in protecting OMSCs from H2O2-induced apoptosis." (PMID 33195247, 2020). "Herein, we demonstrate that augmenting TPP1 can enhance the therapeutic efficacy of aged MSCs in myocardial infarction." (PMID 33195247, 2020). "In our previous study, TPP1 expression was found to be upregulated in SIRT1-overexpressing OMSCs, which significantly enhanced the ability of these cells to survive after injection following myocardial infarction." (PMID 33195247, 2020).
neuroblastoma (1 paper, 2020). Neuroblastoma (NB) is the most common solid, extracranial childhood tumor. "Furthermore, pull-down of the AMPylated proteins from neuroblastoma cells under FICD E234G OX conditions revealed a general increase in AMPylation including proteins such as CTSB, TPP1, CAPZB, and NSFL1C, which were found AMPylated in COs." (PMID 31980631, 2020).
neuronal ceroid lipofuscinosis type 1 (1 paper, 2022). "Enzymatic activity determined on dried blood spots was the main method used to screen for TPP1 and palmitoyl protein thioesterase 1 (PPT1) for the differential diagnosis with neuronal ceroid lipofuscinosis type 1 (NCL1)." (PMID 35425725, 2022).